SUN5 (Sad1 and UNC84 domain containing 5)
Description:
Required for male fertility. Plays an essential role in maintenance of sperm head-to-tail attachment during late stages of spermiogenesis, via promoting secure attachment of the nuclear envelop to the flagellum coupling apparatus (Probable). Component of the LMNB1/SUN5/SEPT12 bridge that connects the sperm proximal centriole to the implantation fossa, the bridge functions to prevent detachment of the proximal centriole from the posterior nucleus during spermiogenesis. Required for localization of SEPT12 at the implantation fossa of sperm cells during spermiogenesis (By similarity).
Synonyms: SPAG4L; TSARG4; dJ726C3.1; SPGF16
Tractability: Antibody: UniProt predicts a signal peptide or a membrane-spanning region.
Gene: Protein-coding gene on chromosome 20 (32,983,773 to 33,004,433, reverse strand). Ensembl gene ENSG00000167098.
Subcellular location: Nucleus inner membrane; Golgi apparatus
Gene Ontology:
Molecular function: protein binding
Biological process: spermatid development; spermatogenesis
Cellular component: nuclear inner membrane; sperm head-tail coupling apparatus; Golgi apparatus; meiotic nuclear membrane microtubule tethering complex
Genetic constraint (gnomAD): Loss-of-function variants: 46 observed, 51.33 expected, observed/expected ratio (o/e) 0.9, 90% interval 0.71 to 1.15. The upper end of that interval is the gene's LOEUF score, 1.15, which puts it in group 5 of 6, group 1 being the genes least tolerant of losing a copy. Missense variants: 421 observed, 458.52 expected, observed/expected ratio (o/e) 0.92, 90% interval 0.85 to 1. Synonymous variants: 164 observed, 169 expected, observed/expected ratio (o/e) 0.97, 90% interval 0.85 to 1.11.
Homologues: Orthologues: chimpanzee SUN5 (95% identical), macaque SUN5 (94% identical), rabbit SUN5 (84% identical), dog SUN5 (79% identical), pig SUN5 (76% identical), guinea pig SUN5 (76% identical), rat Sun5 (76% identical), mouse Sun5 (73% identical), Caenorhabditis elegans unc-84 (21% identical). Paralogues in human: SPAG4 (34% identical), SUN2 (27% identical), SUN1 (26% identical), SUN3 (23% identical).
Diseases named in the same sentence as SUN5 in open-access papers:
SUN5 is named in the same sentence as 12 diseases in open-access papers, as found by Europe PMC text mining. Sharing a sentence is not in itself a finding about the gene and the disease. The quoted sentences say what the papers report.
male infertility (6 papers, 2017 to 2021). The inability of the male to effect fertilization of an ovum after a specified period of unprotected intercourse. "In this study, we generated Sun5–/– mice and found that Sun5 deletion caused decapitated sperm in the epididymis, resulting in the phenotype of acephalic spermatozoa and male infertility." (PMID 34268309, 2021). "This phenotype appears in accordance with several cases of male infertility due to Sun5 gene mutations that induce SUN5 loss or variant production associated to acephalic SPZ syndrome, a form of teratozoospermia characterized by headless SPZ in the ejaculate." (PMID 33925685, 2021). "Our studies reveal the essential role of SUN5 in anchoring sperm head to the tail and provide a promising way to treat this kind of acephalic spermatozoa-associated male infertility." (PMID 28945193, 2017). "In contrast, disruption of Sun5/Spag4l in mice caused male infertility by sperm decapitation." (PMID 34571916, 2021). "Sperm decapitation and male infertility were also observed when the outer dense fibre protein ODF1 or one of its interacting proteins centrosomal protein coiled-coil domain containing 42 (CCDC42) or the testis-specific SUN-domain protein SPAG4L/SUN5 were mutated." (PMID 32859975, 2020). "In conclusion, our results confirm that SUN5 is the main causal gene of ASS and that WES is efficient to identify single gene defects in a context of severe male infertility." (PMID 33671757, 2021). "Ablation of SUN5 leads to male infertility and sperm malformation." (PMID 28945193, 2017).
acephalic spermatozoa syndrome (4 papers, 2017 to 2021). "Studies on the finer structure of spermatozoa development and the interaction between SUN5 and Nesprin3 explained the mechanism underlying the abnormal expression of SUN5 causing acephalic spermatozoa syndrome, providing new insights into the sperm head-to-tail linkage." (PMID 34268309, 2021). "Together with our previous report and other’s paper about SUN5-associated mutations in acephalic spermatozoa syndrome patients, our studies demonstrate that defects in SUN5 may be the major cause of the acephalic spermatozoa syndrome." (PMID 28945193, 2017). "Further research on the molecular mechanism by which Sun5 mediates sperm head-to-tail connections and gene therapy in acephalic spermatozoa with Sun5 mutations is needed, which is of significance to understand the pathogenesis and clinical treatment of acephalic spermatozoa syndrome." (PMID 34268309, 2021). "In this study, we generated Sun5 knockout mice and found that the head-to-tail linkage was broken in Sun5–/– mice, which was similar to human acephalic spermatozoa syndrome." (PMID 34268309, 2021). "Here the authors demonstrate that CENTLEIN links and controls the interaction between SUN5 and PMFBP1, indicating that its impairments might be associated with acephalic spermatozoa syndrome." (PMID 34389728, 2021). "Defects in SUN5 and PMFBP1 are the most common etiologies of human acephalic spermatozoa syndrome, as identified by different investigators and demonstrated in a mouse model." (PMID 34422805, 2021). "We demonstrate that CENTLEIN directly interacts with both SUN5 and PMFBP1, two proteins localized in the HTCA and related with acephalic spermatozoa syndrome." (PMID 34389728, 2021).
Globozoospermia (3 papers, 2017 to 2024). Any structural anomaly of the acrosome resulting in a round sperm head. "When epididymal spermatozoa of a Sun5-deficient mouse were evaluated for the first time, their ‘round-headed’ shape resembled those being present in globozoospermia." (PMID 33260574, 2020). "As round-headed spermatozoa or globozoospermia usually result from an acrosome biogenesis defect or a complete loss of acrosome, these results appear to support a physiological function for SUN5 in acrosome biogenesis." (PMID 28945193, 2017). "Most Sun5-null spermatozoa displayed a globozoospermia-like phenotype but they were actually acephalic spermatozoa." (PMID 28945193, 2017). "Now, the condition caused by the absence of SUN5 is called pseudo-globozoospermia due to the absence of a sperm head." (PMID 33260574, 2020). "Given that Sun5-null spermatozoa are actually pseudo-globozoospermia that do not contain chromatin in the round head, the regular ICSI protocol cannot be applied to these mice or patients." (PMID 28945193, 2017).
infertile (3 papers, 2017 to 2021). "To estimate the age of the c.211+1_211+2dupGT variant identified in ASS infertile men, we used the size of the shared ancestral haplotype surrounding the SUN5 insertion locus." (PMID 33671757, 2021). "(E) Pedigree of family 1 with inherited SUN5 mutations, and the healthy baby of the infertility patient after ICSI." (PMID 28945193, 2017). "Most of the spermatozoa in our recently reported infertile patients with SUN5 mutations are ‘pin headed,’ and thus, they are different from the mice model." (PMID 28945193, 2017). "(G) Pedigree of family 8 with inherited SUN5 mutations, and the health baby of the infertility patient after ICSI." (PMID 28945193, 2017). "Infertility caused by SUN5 mutations could be overcome by ICSI." (PMID 28945193, 2017). "Even though males with acephalic spermatozoa are categorized as infertile, the SUN5 defects can be overcome by intracytoplasmic sperm injection (ICSI), however, regular protocol when the relatively intact sperm is chosen cannot be applied in the case of Sun5 mutant mice or patients." (PMID 33260574, 2020).
teratozoospermia (2 papers, 2021). "Like the other severe monomorphic teratozoospermias, ASS has a strong genetic basis and is most often caused by bi-allelic variants in SUN5 (Sad1 and UNC84 domain-containing 5)." (PMID 33671757, 2021).
colorectal cancer (1 paper, 2022). A primary or metastatic malignant neoplasm that affects the colon or rectum. "Further research on the role of SUN5 in drug sensitivity and self-renewal is essential, which is important for the diagnosis and treatment of colorectal cancer." (PMID 36358787, 2022). "In the present study, we demonstrated that SUN5 was highly expressed in colorectal cancer (CRC) tissues and cells, as indicated by bioinformatics analysis, and SUN5 promoted cell proliferation and migration in vitro." (PMID 36358787, 2022).
gastric cancer (1 paper, 2022). A primary or metastatic malignant neoplasm involving the stomach. "To investigate the expression of SUN5 in different tumor tissues, we collected clinical colorectal, liver, lung, esophageal, and gastric cancer tissues and found that SUN5 was detected in all cancer tissues, and especially highly expressed in CRC tissues." (PMID 36358787, 2022).
lymph node metastasis (1 paper, 2022). "Furthermore, we summarized and analyzed the clinicopathological characteristics of these 40 cases and found that the high SUN5 expression was associated with poor differentiation and lymph node metastasis." (PMID 36358787, 2022).
cancer (1 paper, 2022). A tumor composed of atypical neoplastic, often pleomorphic cells that invade other tissues. "We found that SUN5 was highly expressed in some cancers, but its function and mechanism in cancer development remain unclear." (PMID 36358787, 2022).
tumor (1 paper, 2022). "Overexpression of SUN5 promotes cell proliferation and migration in vitro and accelerates tumor formation in vivo." (PMID 36358787, 2022). "The results revealed that the expression of E-cadherin was downregulated, and N-cadherin, vimentin, Cyclin D1, and pERK1/2 were upregulated in SUN5-OE tumor tissues (p < 0.05), which is consistent with in vitro results." (PMID 36358787, 2022). "The xenograft transplantation experiment showed that SUN5 accelerated tumor formation in vivo." (PMID 36358787, 2022).
SUN5 also shares sentences with these, for which no sentence is quoted: bronchial hyperreactivity (1 paper); macrozoospermia (1).